TLR5 (toll like receptor 5)
Diseases named in the same sentence as TLR5 in open-access papers (continued):
Sharing a sentence is not in itself a finding about the gene and the disease.
infectious disease (6 papers, 2009 to 2023). A disorder directly resulting from the presence and activity of a microbial, viral, or parasitic agent in humans. "This would suggest that the interactions between flagellins and bovine TLR5 are drivers of evolutionary changes which may have functional consequences in terms of both infectious disease susceptibility and/or inflammatory disorders as described for humans." (PMID 25827709, 2015). "For instance, mutations in TLR2, TLR4, TLR5 and IRAK4 have all been associated with increased risk to develop infectious diseases." (PMID 19859543, 2009). "Flex-sweep also identified sweep windows in TLR5 (Toll-like receptor 5), ITGAE (integrin subunit alpha E), and APOL1 (apolipoprotein L1), all previously identified as sweeps associated with infectious diseases or pathogen response by both genomic and functional studies." (PMID 37307561, 2023).
neurodegenerative disease (3 papers, 2018 to 2024). A disorder of the central nervous system characterized by gradual and progressive loss of neural tissue and neurologic function. "We report herein that TLR5 is abundantly expressed in adult microglia whose activation represents a major hallmark in neurodegenerative diseases, and that signaling through this receptor contributes to neuronal apoptosis." (PMID 32912327, 2020). "Although TLR5 has previously been implicated in different CNS disorders including neurodegenerative diseases, its mode of action in the brain remained largely unexplored." (PMID 32912327, 2020). "However, additional studies are needed to elucidate the effects of TLR5 in neurodegenerative diseases and to comprehend its role in microglia." (PMID 30333729, 2018).
respiratory disease (2 papers, 2014). "With regards to the in vivo relevance, the major Pasteurellaceae bacterial pathogens causing bovine respiratory disease do not possess flagella, suggesting that TLR5 stimulation is not important in pathogenesis of this disease." (PMID 25304258, 2014).
TLR5 also shares sentences with these, for which no sentence is quoted: Hypertension (8 papers); glomerulonephritis (7); lupus nephritis (6); nephritis (6); immunodeficiency (5); Hyperglycemia (4); Splenomegaly (4); atopic dermatitis (2); breast tumors (2); hepatitis B (2); intestinal diseases (2); intestinal infection (2); irritable bowel syndrome (2); kidney disease (2); lung disease (2); multiple sclerosis (2); sarcoidosis (2); -dependent (1); AIDS (1); alcohol abuse (1); amoebiasis (1); anemia (1); Atherosclerotic lesion (1); Bovine mastitis (1); breast adenocarcinoma (1); bronchiectasis (1); brucellosis (1); bubonic plague (1); celiac disease (1); cholestasis (1).
A further 54 diseases each share a sentence with TLR5 in 1 paper.